MUC1 (mucin 1, cell surface associated)
Diseases named in the same sentence as MUC1 in open-access papers (continued):
Sharing a sentence is not in itself a finding about the gene and the disease.
tumor (continued). "Recently, in a ranking of 75 tumor antigens based on characteristics such as therapeutic function, immunogenicity, oncogenicity, and specificity, MUC1 received the second-best rating (after WT1), underlining its potential for medical research and vaccine development." (PMID 37894512, 2023). "MUC1 is also associated with tumor associated macrophage-induced lung cancer stem cell progression." (PMID 36895477, 2023). "SIGLEC-9-positive immune cells were associated with several types of MUC1-positive tumor cells." (PMID 36688997, 2023). "And anti-MUC1 responses contributed to epitope spreading against other tumor associated antigens." (PMID 36895477, 2023). "However, the MUC1 expression was associated with the aggressive pathological features related to poor prognostic outcomes, including a higher rate of deeper tumor depth, lymph node, and distant metastasis." (PMID 36831343, 2023). "MUC-1 is a tumor-associated antigen that is glycosylated in tumor cells." (PMID 37007133, 2023). "Further studies with a larger sample size may be needed to confirm the association of the MUC1 staining pattern with tumor malignancy." (PMID 37002293, 2023). "This clearly indicates the potential clinical application of MUC-1 as a tumour associated antigen." (PMID 37686543, 2023). "MUC1 is a transmembrane oncoprotein implicated in cell–cell and cell–extracellular matrix adhesion, which contributes to immune escape and has been linked to transformation, invasion and progress of tumor cells." (PMID 36765559, 2023). "In addition, MUC1 expression loses apical–basal polarity, which causes the redistribution of MUC1 over the tumor cell surface." (PMID 37489369, 2023). "Some of the tumor-associated antigens (TAAs) that could be potential targets for peptide vaccines in CCA are MUC1 and Wilms’ tumor protein 1 (WT1)." (PMID 35743107, 2022). "In HBC, known mutations of MUC-1 gene occurs as somatic changes within tumor genome." (PMID 35000604, 2022). "Finally, immunological recognition of tumor-associated MUC1 is achieved using a completely manufactured aberrantly glycosylated MUC1 tripartite vaccine." (PMID 36497322, 2022). "Therefore, antibodies against tumour-associated MUC1 are binding to the antigen on the surface of cancer cells, and not to normally glycosylated form of MUC1 on the surface of normal cells." (PMID 35351156, 2022). "In addition to neoantigens, tumor-associated antigens such as carcinoembryonic antigen (CEA) or mucin 1 (MUC1) have also demonstrated the ability to elicit an immune response." (PMID 36077639, 2022). "Another prominent glycoprotein in the context of cancer is MUC1, a highly glycosylated transmembrane mucin, that has also been reported to be a carrier of STn in multiple cancer types, and whose overexpression has been linked to tumor growth and metastization." (PMID 35205658, 2022). "Furthermore, the major characteristics making MUC1 an appropriate antibody-based therapeutic target are a significantly increased MUC1 expression within epithelial tumors, an apical-basal polarity loss of tumor cells, and MUC1 expression on a cell surface." (PMID 35883508, 2022). "The high level of MUC1 expression in tumor cells may be associated with dysregulation between the two." (PMID 35883508, 2022). "Clear associations were found between tumor size and the soluble MUC1-level." (PMID 35406491, 2022). "The loss of MUC1 tolerance resulted in a potent anti-tumor response." (PMID 36298592, 2022). "Several larger studies have reported associations between tumor size, nodal status, and MUC1." (PMID 35406491, 2022). "Notably, the major tumor cluster enriching for MUC1-high expression was associated with decreased estimates of immune cell infiltration." (PMID 33495298, 2021). "To test this, we investigated whether the addition of endocytosis inhibitors to tumor cell cultures promoted the expression of tumor-associated MUC1 epitopes." (PMID 34070311, 2021).
tumor (continued). "Notably, high protein expression of MUC1 was associated with more progressive clinical features such as larger tumor size, presence of lymphatic metastasis, advanced tumor stage, vascular invasion 28,38." (PMID 34729096, 2021). "In addition, the tumor-associated MUC1 glycoform bearing the sialyl T antigen was shown to impair the differentiation of DCs and impede their ability to produce interleukin-12 (IL-12)." (PMID 34638920, 2021). "MUC1 expression on the stroma-facing surface of the cells might be a key factor contributing to the distinct morphology of this tumor type by causing the detachment of neoplastic cells from the stroma." (PMID 33761962, 2021). "As such, tumour-associated MUC1 may be targeted due to its inherent structural changes found only in tumour tissues." (PMID 34830751, 2021). "MUC1 has been implicated in the induction of immunosuppressive tumor microenvironment." (PMID 33692796, 2021). "Similarly, placental derived GRP94 was found to bind to tumor-associated antigens such as HER2 and MUC1 and induce tumor-specific T cell responses." (PMID 33898309, 2021). "Notably, the conjugated murine mAb C595 (targeting the core epitope) has shown success in radiolabelling and identifying tumour-associated MUC1-overexpressed EOC." (PMID 34830751, 2021). "Breast-specific tumor-associated antigens such as mammaglobin, MUC1, and lactalbumin may provide a broader range of coverage in a preventative setting, but studies utilizing these proteins in targeted therapies are still in their infancy." (PMID 34899753, 2021). "MUC1 has garnered great interest during the course of mucin research, and the clinical application of MUC1 as a vaccine for activating the immune response against tumour‐associated antigens has been investigated." (PMID 32745356, 2020). "Most of those studies are based on BCG expressing MUC1 and adding or co-expressing some other immunostimulatory molecules, such as cytokines or chemokines, in order to improve the relatively poor immunogenicity of this breast-tumor-associated antigen." (PMID 32635668, 2020). "In addition, mTECs have been shown to express other tumor-associated antigens such as MUC1 and CEA51." (PMID 32641748, 2020). "Here we show that a sialylated tumour-associated glycoform of the mucin MUC1, MUC1-ST, through the engagement of Siglec-9 can specifically and independently induce the differentiation of monocytes into TAMs with a unique phenotype that to the best of our knowledge has not previously been described." (PMID 33149188, 2020). "MUC-1 downstream signaling molecules, such as Src, PI3k, and Akt, were also downregulated in O-glycan deficient mice, indicating a role in decreased proliferation and tumor suppression." (PMID 32075174, 2020). "Studies show that MUC1 is associated with tumor initiation and progression." (PMID 30699986, 2019). "In addition, LeIF has been used as adjuvant to promote the induction of Th1-type immune response against the tumor-associated MUC1 tandem repeat peptide in a chimpanzee animal model." (PMID 31183394, 2019). "Our data corroborates that tumor-associated MUC1 remains a critical targetable antigen in PDA." (PMID 31514488, 2019). "This under-glycosylation exposes the MUC1 protein core on the tumor-associated form of the protein." (PMID 31693710, 2019). "Moreover, immunoblotting assays demonstrated reactivity to tumour-associated O-glycosylated proteins, such as MUC1." (PMID 30111774, 2018). "Abnormally O-glycosylated MUC1 tandem repeat glycopeptide epitopes expressed by multiple types of cancer have long been attractive targets for therapy in the race against genetic mutations of tumor cells." (PMID 29857542, 2018). "This suggests that the complexity immune microenvironment of the involution gland in MUC1-CD transgenic mice may be associated with tumor progression." (PMID 29423058, 2018).
tumor (continued). "MUC1 mucin is normally expressed by secretory epithelial cells but has been implicated as a tumor antigen for various vaccine immunotherapeutic studies targeting the generation of B and T cell responses because it is abundantly expressed in aberrant forms by a number of adenocarcinoma tumor cells." (PMID 30405607, 2018). "c-Src is also associated with MUC1-CT and plays a vital role in MUC1 induced tumor metastasis." (PMID 29467938, 2018). "It must be noted that in these KCM mice, all other glandular epithelial organs express normal human MUC1 but TAB004-ICG only accumulates in the pancreas post initiation of oncogenesis suggesting the high specificity of TAB004 to transformed/tumor associated form of MUC1." (PMID 29462213, 2018). "Indeed, the sialylated tumor antigens, such as Sialyl-Tn (sTn) and Sialyl-T (sT) expressed in mucins, namely MUC1, were associated with tumor immune tolerance." (PMID 30538706, 2018). "Antibody targeting MUC1 may block MUC1-induced expression of genes associated with tumor invasion, angiogenesis and metastases and restore immune surveillance suppressed by abnormally overexpression of MUC1 on cancer cells." (PMID 29857542, 2018). "Besides, the mucin MUC1 containing multiple short, sialylated O-linked glycans (MUC1-ST) on tumor cells facilitate the tumor-associated macrophages to acquire the protumoral phenotype by binding with Siglec-9 receptor." (PMID 29899741, 2018). "The tumor-associated form of MUC1 plays an important role in oncogenic signaling." (PMID 29467938, 2018). "Both the tumor MV samples carried the MUC1 tumor-associated glycoprotein." (PMID 28993771, 2017). "Investigators may design CARs targeting aberrantly modification of TAAs or tumor-specific oncogenic mutations such as truncated MUC1." (PMID 29312360, 2017). "In addition to its increased expression level and the loss of its apical expression pattern on tumor cells, MUC1 is recognized as a tumor-associated antigen following post-translational modifications rather than mutations in its coding sequence." (PMID 28679396, 2017). "We analyzed the tumor-associated transcripts EpCAM, MUC-1 and CA-125." (PMID 28388557, 2017). "It is possible that, like galectin-3, the increased interactions of these galectin members with cancer-associated TF/MUC1/4 in circulation may also influence tumor cell metastatic spread." (PMID 27066458, 2016). "We next investigated whether T-cells from mice vaccinated with different MUC1 preparations recognized tumor-associated MUC1 as well as synthetic peptides." (PMID 26788922, 2016). "The association of MUC1 expression with adverse pathological features suggests that MUC1 could have utility as a biomarker for predicting tumor upgrading or upstaging." (PMID 27846218, 2016). "One protein, CIN85, was identified recently, which associates with MUC1 in tumor cells." (PMID 26528431, 2015). "The cellular immunological responses and protection from tumor challenge exhibited by this CpG-containing formulation could induce MUC1-specific CTLs and cause growth inhibition of MUC1-expressing tumors." (PMID 26417929, 2015).
tumor (continued). "MUC1-C is a transmembrane subunit of MUC1 glycoprotein that accumulates in the cytoplasm and is associated with β-catenin to translocate into the nucleus in triggering expression of cancer-related oncogenes associated with tumor progression." (PMID 25762620, 2015). "Overexpression of MUC1 has been associated with more aggressive GCC tumor biology." (PMID 25671432, 2015). "Patients with over expressed MUC1 may need more radical or aggressive treatment after diagnosis and more rigorous care after tumor resection due to a relatively high risk of metastasis." (PMID 26367866, 2015). "The results suggested that MUC1 rs4072037 polymorphism might be involved in gastric carcinogenesis and tumor differentiation among Asian populations." (PMID 24755768, 2014). "Given that MUC1 is known to regulate transcription of a number of processes associated with tumor progression, we hypothesized that transcription of miR-200c was regulated by signal transduction through MUC1." (PMID 24143167, 2013). "A novel antibody, PankoMab, was developed against a tumor-associated epitope of MUC1." (PMID 23890049, 2013). "In contrast, we characterized the adhesive role of tumor associated MUC1 under hydrodynamic shear stress by perfusing both ZR-75-1 (which overexpresses MUC1) and MCF7 cells through functionalized microtubes, more representative of the blood vessel microenvironment." (PMID 22866263, 2012). "Expression of GdC15, GdQ13 and GdA epitopes rose with positivity for PankoMabGEXTM (GdC15, p = 0.007; GdQ13, p = 0.010; GdA, p = 0.004), which recognizes a special tumour-associated epitope on MUC1, TA-MUC1, that either localizes to the cell membrane (mPankoMabGEXTM) or cytoplasm (cPankoMabGEXTM)." (PMID 23036050, 2012). "Importantly, following EGF treatment, we detected elevated transcript levels of several MUC1 target genes linked to tumor cell invasion including TWIST, SNAI1, and SNAI2." (PMID 22586492, 2012). "ImMucin, which is being evaluated in multiple myeloma patients, consists of a synthetic peptide composed of the entire signal peptide domain of the MUC1 that is expressed only on tumor cells in association with MHC molecules, thereby ensuring specific anti-cancer activity." (PMID 24970145, 2012). "In normal tissue, the protein core of MUC1 is usually shielded by the saccharide chains; whereas in tumor cells, the protein core is exposed due to deficient glycosylation, allowing the tandem repeat sequences to serve as potential target for anticancer therapy." (PMID 22384115, 2012). "Moreover, EGF-induced transcription was abolished by MUC1 knockdown, supporting a critical role for MUC1 in the EGF-dependent transcription of genes linked to tumor cell invasion." (PMID 22586492, 2012). "Many studies have revealed that this event could be linked to the presence of membrane-associated MUC1 molecular portions that are shed from the surface of tumour cells to the cytosol by modulation of its glycosylation state." (PMID 22726603, 2012). "In addition, we examined the effect of GalNAc glycosylation of a physiological tumor associated MUC1 glycopeptide known to induce CD4+ and CD8+ T cell responses." (PMID 23189185, 2012). "MUC1 is expressed by tumor cells with a deficiency in glycosylation." (PMID 23023583, 2012). "The binding of IIB6 to native tumour associated MUC1 was analysed by flow cytometry." (PMID 21264246, 2011). "The pattern of reactivity exhibited by serum samples from patients with adenocarcinoma can be explained by the reduced glycan chain lengths on tumor-associated MUC1, which facilitate the accessibility to the invariant peptide core, and enable immune responses to it." (PMID 24212946, 2011). "The findings suggest that H. pylori infection may induce an immune response to tumor-associated MUC1." (PMID 24212946, 2011). "However, a deficiency of Muc1 results in both reduced tumor growth and spreading in MMTV1-mTag mice." (PMID 21533058, 2011).
tumor (continued). "Antibodies bound to the mucin may curb tumor progression by restoring cell-cell interactions altered by tumor-associated MUC1, thus preventing metastatic dissemination, as well as counteracting the immune suppression exerted by the molecule." (PMID 24212946, 2011). "Thus, an increase of tumour cell aggregation as a result of the increased interaction between circulating galectin-3 and cancer-associated MUC1 in cancer patients provides a survival advantage to the disseminating tumour cells in the circulation." (PMID 20565834, 2010). "Induction of the MAPS by MUC1-CD and its association with cell proliferation suggested that expression of this signature might identify an aggressive tumor phenotype." (PMID 20459602, 2010). "Based on these findings and on in vitro data, it was hypothesized that spontaneously occurring anti-MUC-1 antibodies might bind to the surface of tumor cells uncovering adhesion molecules masked by the deficiently glycosylated MUC-1." (PMID 21234352, 2010). "Nevertheless, this may be of major importance as suggested by the tumour antigen MUC-1 whose hypoglycosylated variant expressed in tumour tissue is differentially recognised by mucin-specific antibodies." (PMID 17622246, 2007). "Vectors representing circulating immune complexes were associated with advanced tumor T stage which may indicate that a large tumor mass produces the MUC1 mucin that reacts with antibodies, forming circulating immune complexes." (PMID 17064405, 2006). "This could be accounted for by differences the level or quality of tumour-associated MUC1 expression on the cells used but supports the relevance of native antigen." (PMID 16265351, 2005). "Probably, in the context of the tumor microenvironment, among the different carcinogenic mechanisms, a sialylated glycoform associated with tumor-associated MUC1 could induce the differentiation of monocytes into tumor-associated macrophages (TAMs), which in turn become mast cells." (PMID 41295249, 2025). "In addition, modifications of MUC1 cell surface localization, in response to Gal-3 binding, cause homotypic aggregation of cancer cells and the development of circulating tumor emboli, thereby avoiding anoikis and extending the duration of neoplastic cell survival." (PMID 40001578, 2025). "Indeed, the tumor-associated MUC1 (tMUC1) is characterized by an extensive loss of O-glycosylation." (PMID 40001578, 2025). "The cancer-specific MUC1 glycoforms, carrying the sialylated core 1 glycan (α2,3-MUC1-sT), could induce macrophages to display a tumor-associated phenotype (TAM), also defined as alternatively activated (M2) pro-tumorigenic macrophages, through the engagement of Siglec-9." (PMID 38611013, 2024). "Moreover, MUC1 increases PD-L1 expression directly at the transcriptional level, induces primary healthy monocytes to differentiate into macrophages with a tumor-associated macrophage M2-like (TAM2) phenotype, and decreases MCP1, IFN-gamma, and GM-CSF expression." (PMID 38540735, 2024). "Also, according to the literature, mucins are normally produced by goblet cells, but via inflammation and in tumors, their numbers decrease, the secretion of proteins decreases, and high Muc1 expression during tumor growth is associated with increased invasion and metastasis." (PMID 39063041, 2024). "Tumor-associated MUC1 has long been considered as a potential target molecule that might be able to elicit an immune response that then provides protection against MUC1-expressing tumor cells." (PMID 36980805, 2023).